PPDPF (pancreatic progenitor cell differentiation and proliferation factor)
Description:
Probable regulator of exocrine pancreas development.
Synonyms: C20orf149; dJ697K14.9; exdpf
Tractability: PROTAC: ubiquitination databases record sites on it.
Gene: Protein-coding gene on chromosome 20 (63,520,754 to 63,527,076, forward strand). Ensembl gene ENSG00000125534.
Subcellular location (Human Protein Atlas): Microtubules; Nucleoplasm; Nucleoli
Gene Ontology:
Biological process: cell differentiation
Cellular component: mitochondrion
Genetic constraint (gnomAD): Loss-of-function variants: 11 observed, 6.47 expected, observed/expected ratio (o/e) 1.7, 90% interval 0.99 to 1.95. That is too few expected variants to judge how well the gene tolerates losing a copy. Missense variants: 202 observed, 162.54 expected, observed/expected ratio (o/e) 1.24, 90% interval 1.11 to 1.4. Synonymous variants: 86 observed, 66.66 expected, observed/expected ratio (o/e) 1.29, 90% interval 1.08 to 1.54.
Homologues: Orthologues: chimpanzee PPDPF (98% identical), macaque PPDPF (96% identical), mouse Ppdpf (67% identical), tropical clawed frog ppdpf (62% identical), dog PPDPF (61% identical), rat Ppdpf (61% identical), zebrafish ppdpfb (56% identical), zebrafish ppdpfa (50% identical). Paralogues in human: PPDPFL (25% identical).
Diseases named in the same sentence as PPDPF in open-access papers:
PPDPF is named in the same sentence as 19 diseases in open-access papers, as found by Europe PMC text mining. Sharing a sentence is not in itself a finding about the gene and the disease. The quoted sentences say what the papers report.
Hepatic steatosis (2 papers, 2021 to 2025). Steatosis is a term used to denote lipid accumulation within hepatocytes. "Here, the authors show that PPDPF inhibits the development of hepatic steatosis by negatively regulating mTORC1-S6K-SREBP1 signaling, which provides a potential therapeutic candidate for NAFLD treatment." (PMID 34031390, 2021). "In this study, we find that liver-specific knockout of PPDPF (PPDPF-LKO) leads to spontaneous fatty liver formation in a mouse model at 32 weeks of age on chow diets, which is enhanced by HFD." (PMID 34031390, 2021). "The dysregulation of mTOR promotes hepatic steatosis through SREBP-mediated lipogenesis, while liver-specific PPDPF deletion induces spontaneous fatty liver by negatively regulating the mTORC1-S6K-SREBP1 signaling pathway." (PMID 40868109, 2025). "Accordingly, liver-specific PPDPF overexpression effectively inhibits HFD-induced mTOR signaling activation and hepatic steatosis in mice." (PMID 34031390, 2021). "However, the role of PPDPF in hepatic steatosis has not been elucidated." (PMID 34031390, 2021).
lung carcinoma (2 papers, 2022 to 2023). "Meanwhile, an increased protein level of γH2AX was found in lung cancer cells with PPDPF knockdown upon irradiation and the restore time to the basal level was longer." (PMID 34975328, 2022). "The results showed that the protein level of PPDPF was relatively high in the lung cancer cell lines." (PMID 34975328, 2022). "Knockout of PPDPF expression in the KL mouse model of lung cancer inhibited tumorigenesis de novo, improving the survival of the mice." (PMID 34975328, 2022). "In the colony formation assay and CCK-8 assay, overexpression of PPDPF promoted the growth of lung cancer cells in liquid culture." (PMID 34975328, 2022). "To further confirm these observations, we examined the protein level of PPDPF in a lung cancer tissue array (containing 90 lung cancer tissues and 88 paired adjacent tissues)." (PMID 34975328, 2022). "It was found that the protein level of PPDPF was significantly elevated in lung cancer tissues (10/12)." (PMID 34975328, 2022). "Knockdown of PPDPF promoted radiotherapy-induced apoptosis of lung cancer cells, and overexpression of PPDPF inhibited radiotherapy-induced apoptosis." (PMID 34975328, 2022). "It was discovered in this study that the expression of PPDPF was upregulated in clinical specimens of lung cancer and that the PPDPF expression level was significantly correlated with the prognosis of patients." (PMID 34975328, 2022). "We first analyzed the GSE31210 lung cancer dataset, and the results suggested that the expression of PPDPF was upregulated in the lung cancer tissues." (PMID 34975328, 2022). "In this study, we investigated the expression pattern of PPDPF in lung cancer, the effect of PPDPF on the resistance of lung cancer to treatment, and attempted to further elucidate the underlying mechanism." (PMID 34975328, 2022). "The results of the crystal violet assay and CCK-8 assay showed that knockdown of PPDPF inhibited the growth of lung cancer cells in liquid medium." (PMID 34975328, 2022). "Moreover, downregulation of PPDPF inhibited the anchorage-independent growth of lung cancer cells and weakened the invasion ability of lung cancer cells." (PMID 34975328, 2022). "In addition, the protein level of PPDPF was examined in the 12 adjacent tissues and paired tumor tissues derived from the lung cancer patients." (PMID 34975328, 2022). "Moreover, the EdU incorporation assay showed that forced expression of PPDPF promoted the proliferation of lung cancer cells." (PMID 34975328, 2022). "PPDPF promoted the growth, colony formation and invasion of lung cancer cells." (PMID 34975328, 2022). "PPDPF promoted the growth, invasion and tumorigenic ability of lung cancer cells." (PMID 34975328, 2022). "Western blotting was performed to measure the protein level of PPDPF in lung cancer cells." (PMID 34975328, 2022). "Moreover, knockout of PPDPF inhibited tumorigenesis in the KL (KrasG12D; LKB1f/f) mouse model of lung cancer." (PMID 34975328, 2022). "Next, the effect of PPDPF expression on the tumorigenicity of lung cancer cells was explored." (PMID 34975328, 2022). "Additionally, overexpression of PPDPF led to radioresistance in lung cancer cells, and knockdown of PPDPF sensitized lung cancer cells to radiotherapy." (PMID 34975328, 2022). "In addition, we examined the expression pattern of PPDPF in lung cancer samples and cell lines." (PMID 34975328, 2022). "In summary, this study revealed that the expression of PPDPF is upregulated in lung cancer and inhibits the degradation of BABAM2, thereby enhancing the resistance of lung cancer cells to radiotherapy." (PMID 34975328, 2022). "Mechanistically, PPDPF interacted with BABAM2 (an antiapoptotic protein) and blocked its ubiquitination by MDM2, thus stabilizing BABAM2 and promoting the radioresistance of lung cancer cells." (PMID 34975328, 2022).
lung carcinoma (continued). "In the xenografts formed from cells with PPDPF knockdown, the IHC results showed that the expression of BABAM2 and Bcl-xl was downregulated and that cleaved Caspase3 was upregulated, further demonstrating that downregulation of PPDPF inhibited the tumorigenesis of lung cancer cells in vivo." (PMID 34975328, 2022). "Furthermore, endogenously expressed PPDPF and BABAM2 formed a complex in lung cancer cells." (PMID 34975328, 2022).
non-small cell lung carcinoma (2 papers, 2020 to 2022). A group of at least three distinct histological types of lung cancer, including non-small cell squamous cell carcinoma, adenocarcinoma, and large cell carcinoma. "It has also been demonstrated that circFOXM1 can act as a sponge of miR-1304-5p such as to promote cell progression by regulating PPDPF and MACC1 in examinations of non-small-cell lung cancer-afflicted samples." (PMID 32904557, 2020).
pancreatic cancer (2 papers, 2023 to 2025). "PPDPF, which is highly expressed in pancreatic cancer, regulates the GEF activity of SOS1 to promote disease progression in Kras mutant pancreatic ductal carcinoma." (PMID 40134951, 2025). "The current study revealed that the expression of PPDPF was increased in pancreatic cancer, and patients with high PPDPF expression had a worse prognosis." (PMID 36453576, 2023). "We found that overexpression of PPDPF significantly elevated the level of p‐ERK, a well‐known marker of RAS activation, in pancreatic cancer cells, while PPDPF knockout remarkably decreased the expression level of p‐ERK." (PMID 36453576, 2023).
pancreatic ductal adenocarcinoma (2 papers, 2023 to 2025). An infiltrating adenocarcinoma that arises from the epithelial cells of the pancreas. "The expression of PPDPF is significantly increased in pancreatic ductal adenocarcinoma (PDAC), associated with poor prognosis and recurrence of PDAC patients." (PMID 36453576, 2023).
Achalasia (1 paper, 2023). A disorder of esophageal motility characterized by the inability of the lower esophageal sphincter to relax during swallowing and by inadequate or lacking peristalsis in the lower half of the body of the esophagus. "Analysis of DEGs showed the upregulations of PPDPF, NENF, and CYBA and downregulations of FOS, DUSP1, and GPX1 in peripheral blood myeloid cells of achalasia." (PMID 37542039, 2023).
dementia (1 paper, 2022). Loss of intellectual abilities interfering with an individual's social and occupational functions. "Two genes (PRTN3 and PPDPF) were downregulated in dementia vs. NCI or MCI." (PMID 35557837, 2022).
diabetes (1 paper, 2025). "Since several genes associated with diabetes are involved in PP development, we explored publicly available genetic data for PPDPF association with metabolic traits." (PMID 40193385, 2025). "Importantly, the PPDPF-associated SNPs did not correlate with actual diabetes risk but only with glycaemic alterations thereby supporting the less important role for pancreas development in humans than in zebrafish." (PMID 40193385, 2025).
glioma (1 paper, 2024). A benign or malignant brain and spinal cord tumor that arises from glial cells (astrocytes, oligodendrocytes, ependymal cells). "Additionally, patients with higher PPDPF expression exhibited worse prognosis than others, while high HIST1H2BK levels predicted poor prognosis in glioma patients." (PMID 39121006, 2024).
Glucose intolerance (1 paper, 2021). Glucose intolerance (GI) can be defined as dysglycemia that comprises both prediabetes and diabetes. "In addition, PPDPF overexpression effectively improved HFD-induced glucose intolerance and insulin resistance." (PMID 34031390, 2021). "In conclusion, hepatocyte-specific PPDPF depletion exaggerated HFD-induced lipid droplet accumulation, glucose intolerance and insulin resistance in vivo, as well as PA-induced steatosis in vitro." (PMID 34031390, 2021).
hepatocellular carcinoma (1 paper, 2021). A malignant tumor that arises from hepatocytes. "Aberrant PPDPF expression was correlated with poor prognosis in hepatocellular carcinoma." (PMID 34867976, 2021).
prostate carcinoma (1 paper, 2022). A carcinoma that arises from epithelial cells of the prostate gland. "Recently, PPDPF, JUN and HES4 together are found to be a transcriptomic signature that could predict biochemical recurrence with better accuracy in prostate cancer 29, suggesting a role of PPDPF in the treatment response of cancers." (PMID 34975328, 2022).
steatosis (1 paper, 2021). Increased lipid within the cytoplasm of cells. "Downregulation of PPDPF is also detected in the steatosis liver tissues of patients with NAFLD." (PMID 34031390, 2021). "Moreover, PPDPF overexpression significantly reduced HFD-induced steatosis." (PMID 34031390, 2021).
type 2 diabetes (1 paper, 2025). "The modest effect is in line with the finding that genetic variants near PPDPF are associated with random glucose levels in humans, but not with type 2 diabetes risk, supporting that dysregulation of this gene may only result in minor alterations of glycaemic balance in humans." (PMID 40193385, 2025).
cancer (5 papers, 2020 to 2025). A tumor composed of atypical neoplastic, often pleomorphic cells that invade other tissues. "The list of putative interaction partners generated in HEK293T cells possesses, in our opinion, a valuable resource for future mechanistical studies in the rising field of PPDPF-related cancer studies." (PMID 40193385, 2025). "However, the detailed function and mechanisms of PPDPF in cancer development remains to be elucidated." (PMID 34975328, 2022). "Finally, PPDPF is known to be expressed during pancreas development [Pancreatic Progenitor Cell Differentiation And Proliferation Factor] and differentially expressed in several types of cancer." (PMID 33324443, 2020).
tumor (5 papers, 2021 to 2025). "Mutations of the GTP‐binding sites severely impair the tumor‐promoting effect of PPDPF." (PMID 36453576, 2023). "In conclusion, our study reveals that PPDPF is dispensable for human pancreas development, while current literature suggests an important protein regulatory role of PPDPF during tumor formation and progression in several organs." (PMID 40193385, 2025). "Two weeks after tumor cell implantation, the amount of photons in the PPDPF knockout group was much lower than that in the control group, despite the equal bioluminescent intensity at the beginning." (PMID 36453576, 2023). "Pancreatic‐specific deletion of PPDPF profoundly inhibits tumor development in KRASG12D‐driven genetic mouse models of PDAC." (PMID 36453576, 2023). "Taken together, these data suggested that GTP‐loaded PPDPF enhanced the GEF activity of SOS1, which was indispensable for the tumor‐promoting function of PPDPF in PDAC." (PMID 36453576, 2023). "In summary, the GTP‐binding capability of PPDPF was required for its tumor‐promoting effect via RAS/MAPK signaling." (PMID 36453576, 2023). "Furthermore, several studies have disclosed an oncogenic, pro-proliferative and anti-apoptotic role of PPDPF, while one study postulated a tumor suppressive and anti-proliferative role." (PMID 40193385, 2025). "The substantial degree of species conservation together with the emerging literature on the role of PPDPF for tumor growth supported the hypothesis of a potentially important function of human PPDPF during pancreas development." (PMID 40193385, 2025). "Moreover, knockout of PPDPF significantly inhibited tumor development in the mouse models of KRASG12D‐driven PDAC." (PMID 36453576, 2023). "Our study reported the significantly increased PPDPF expression in PDAC, and found that its expression was associated with tumor size, TNM stage, histological grade, recurrence and survival, indicating it may serve as a prognostic marker for PDAC." (PMID 36453576, 2023). "Next, we asked whether the tumor‐promoting effect of PPDPF in PDAC was SOS1‐dependent." (PMID 36453576, 2023). "Consistent with results of RT‐qPCR, PPDPF expression was significantly increased in the tumor tissues compared to the paired noncancerous tissues." (PMID 36453576, 2023). "Moreover, the expression of PPDPF was higher in tumor tissues in recurrent cases than that in nonrecurrent cases." (PMID 34975328, 2022).
PPDPF also shares sentences with these, for which no sentence is quoted: colorectal cancer (1 paper); infection (1); Insulin resistance (1).